BTK (Bruton tyrosine kinase)
Diseases named in the same sentence as BTK in open-access papers (continued):
Sharing a sentence is not in itself a finding about the gene and the disease.
infection (continued). "Based on these considerations, we hypothesized that dysregulated BTK-dependent macrophage signaling is central to the exaggerated inflammatory responses and pulmonary sequelae of infection with SARS-CoV-2 and potentially other single-stranded RNA viruses." (PMID 32503877, 2020). "We found collectively among SP-A variants several genes such as AKT1, BTK, CCL9, PPARG, and RELA to exhibit higher expression in females, whereas, CFLAR, C1QC, LSP1, CKAP2, KAT2B, TACC2, and RCC2 exhibited higher expression in males after infection." (PMID 32670284, 2020). "fumigatus infection via pharyngeal aspiration in 26 BTK knockout and 20 wild-type mice." (PMID 31372213, 2019). "Although TRAEs of special interest mostly occurred in the early phase after starting administration, 3 patients experienced TRAEs (infection or cytopenia) after 6 months of administration; therefore, careful monitoring may be required for the long-term use of BTK inhibitors." (PMID 38690230, 2024). "One implication of the data presented in this paper is that inhibiting BTK in monocytes and neutrophils, as an off‐target drug effect, could result in their inefficient recruitment of innate immune cells to sites of ongoing infection and result in reduced pathogen clearance." (PMID 34897650, 2022). "Thus, BTK inhibition impairs the anti-bacterial immunity and promotes infection." (PMID 36183125, 2022). "Significantly downregulated of key components of TCR and BCR signaling pathways, such as ZAP70, BTK, and CD79A, suggested a temporary inhibition of these pathways critical for cellular immunity post-infection." (PMID 39650642, 2024). "Vaccination can be an effective measure to prevent infection with SARS‐CoV‐2, but specific treatments such as Bruton's tyrosine kinase (BTK) inhibitors are known to negatively impact humoral vaccine responses." (PMID 36819189, 2023). "Cells were transfected with BTK-targeting small interfering RNA (siRNA) (siBTK) or a negative control (siNC) for 48 h, followed by infection with VACV-WR at 0.01 pfu/cell for an additional 48 h." (PMID 40833106, 2025). "The most common adverse event in patients with CLL is infection (83%) that may be related to the inhibition of ITK in T cells and that of BTK in neutrophils and macrophages." (PMID 36138486, 2022). "In addition, hyper-responsiveness to the infection and enhanced anti-RGNNV activity were suggested by the lower expression of suppressor of cytokine signaling 1 (SOCS1) and BTK." (PMID 35215144, 2022). "Conversely, none of our analyses flagged up BTK as a target in our model of infection, further pointing towards a BTK-independent mechanism of action for Ibrutinib in this context." (PMID 30890742, 2019). "Treatment with a BTK inhibitor before SARS-CoV-2 vaccination, as well as qualitative differences for immune stimulation between vaccination and infection, may also have contributed to the blunted vaccination responses observed in patients with CLL or WM on BTK inhibitors." (PMID 39906744, 2024). "The female mice exhibited higher expression levels of AKT1, BTK, CCL9, and LSP1 (KO, 1A0), PPARG (KO, 1A0, and 6A2), CFLAR, and ERP44 (1A0, 6A4), CCL9 (KO, 1A0, and 6A4), RCC2, and RELA (KO), KAT2B (6A2) and FKBP5 (1A0, 6A2, and 6A4) compared to males in response to infection." (PMID 32670284, 2020). "Since it likely depends on the effect on different pathways and not only on BTK inhibition, it could be speculated that treatment with more selective BTKis, such as acalabrutinib, not affecting the ITK, could result in lower infection rates." (PMID 34276674, 2021).
hematological malignancies (54 papers, 2014 to 2026). "CD81 has been implicated in chemotherapy resistance in hematological malignancies, where it mediates drug tolerance via Bruton’s tyrosine kinase (BTK) signaling in both AML and ALL." (PMID 41415560, 2025). "Overexpression and inappropriate activation of BTK have been implicated in the pathogenesis of several hematologic malignancies." (PMID 36969836, 2023). "Thus, in this multicenter study in Korea, where HBV is prevalent, we describe the fatal side effects of hepatic failure associated with HBV reactivation in patients with hematologic malignancies treated with BTK inhibitors." (PMID 40815495, 2025). "In addition, BCL2A1 was a critical mediator of B‐cell survive and regulated by Spleen tyrosine kinase and Bruton tyrosine kinase, and was associated with advancement of hematological malignancies as well as solid tumor." (PMID 35603962, 2022). "Moreover, patients who have been treated with BTKi only experience neutrophil defects due to BTK inhibition, but they may also exhibit additional immunological impairments arising from their underlying hematological disorder and/or advanced age." (PMID 38696257, 2024). "BTK (Bruton's tyrosine kinase) has become a key therapeutic target across several hematologic diseases, beginning with its original use in CLL/SLL." (PMID 41594662, 2026). "Bruton's Tyrosine Kinase (BTK) is a validated target for hematological malignancies, with numerous FDA-approved inhibitors on the market." (PMID 42130460, 2026). "BTK (Bruton’s tyrosine kinase) is primarily known for its role in B-cell development and signaling, particularly in hematologic malignancies." (PMID 39925800, 2025). "AVL-292, currently in phase 1 clinical trials for hematological malignancies, binds to BTK with high specificity and inhibits its activity, which subsequently impacts on PLCγ2 phosphorylation." (PMID 36612306, 2023). "Tirabrutinib is a highly selective Bruton’s tyrosine kinase (BTK) inhibitor used to treat hematological malignancies." (PMID 36897912, 2023). "Enhancer of zeste homolog 2 (EZH2) and Bruton’s tyrosine kinase (BTK) are both key factors involved in the development and progression of hematological malignancies." (PMID 37752998, 2023). "As a result, the pharmacological suppression of BTK is of great therapeutic benefit not only in B-cell, but in other hematological malignancies as well." (PMID 36969836, 2023). "BTK is a vital part of the signaling pathway downstream from the B-cell receptor (BCR), and its continuous activation is a hallmark of several hematological malignancies." (PMID 35954440, 2022). "CG-806 (luxeptinib) is a dual BTK/SYK inhibitor in clinical development in hematologic malignancies." (PMID 35296646, 2022). "A novel approach with targeting proteins for degradation was applied for Bruton tyrosine kinase (BTK)-driven hematological malignancies." (PMID 35954440, 2022). "BTK is used by MDSC for TLRs, and as such is one of the reasons why BTK inhibitors are successful against hematologic malignancies." (PMID 36294458, 2022). "Ibrutinib, a covalent inhibitor of BTK, can treat hematological malignancies by inhibiting BTK phosphorylation." (PMID 36557960, 2022). "BTK inhibition has been established as an effective strategy for the treatment of B-cell leukemia and other hematological malignancies." (PMID 36294458, 2022). "In this review, we summarized current progress in applying BTK inhibitors in the treatment of hematological malignancies and inflammatory disorders, highlighting available results from clinical studies." (PMID 36183125, 2022). "Given BTK’s role in B-cell and myeloid cell homeostasis, BTK inhibition has been established as an effective strategy for treatment of B-cell leukemia and other hematological malignancies." (PMID 36294458, 2022).
hematological malignancies (continued). "The survival reliance of B cell malignancies on B cell receptor signaling has allowed small molecules that target BTK to become essential tools in treating patients with hematological malignancies." (PMID 34249912, 2021). "Previously, therapeutics targeting Bruton’s tyrosine kinase (BTK) have been successful in treating several hematologic malignancies." (PMID 34315851, 2021). "Ibrutinib is a Bruton’s tyrosine kinase (BTK) inhibitor that is commonly used for the treatment of various hematological malignancies since first approved in November 2013." (PMID 34798905, 2021). "In summary, 5-phenoxy-2-aminopyridine derivatives were designed and synthesized as covalent BTK inhibitors and their in vitro and in vivo effects in experimental models of hematological malignancy were tested." (PMID 33126415, 2020). "Ibrutinib is a Bruton's tyrosine kinase (BTK) inhibitor approved for the treatment of several hematologic malignancies." (PMID 32110454, 2020). "A small-molecule inhibitor of BTK, ibrutinib, had been used for the patients with hematological malignancies." (PMID 32351880, 2020). "Bruton's tyrosine kinase (BTK) and the chemokine receptor CXCR4 are linked in various hematologic malignancies." (PMID 25083818, 2014). "In addition, BTK has recently become an important target in hematological malignancies, with the development of various targeted therapies specifically targeted to inhibit BCR signaling." (PMID 28427156, 2017). "In a meta-analysis including 11,086 patients with hematological malignancies evaluating SARS-CoV-2 vaccine antibody responses, significantly impaired responses were observed in individuals receiving Ruxolitinib or BTK inhibitors." (PMID 40733703, 2025). "Another orally administered small molecule inhibitor of BTK, which has also been reported to have off-target activity against the ERBB/EGFP family, ibrutinib, is an FDA-approved drug for hematological diseases." (PMID 38534733, 2024). "Multiple studies highlighted that patients with hematological malignancies receiving immunosuppressive therapies such as stem cell transplantation, anti-CD20 therapies, Bruton’s tyrosine kinase (BTK) inhibitors and CAR-T cell treatments are at higher risk." (PMID 37529238, 2023). "Targeting BTK with recently developed BTK inhibitors has been approved by the Food and Drug Administration (FDA) for the treatment of several hematological malignancies and has transformed the treatment of several B-cell malignancies." (PMID 34307353, 2021). "Small molecule inhibitors targeting cellular oncoproteins and enzymes such as BCR-ABL, JAK2, Bruton tyrosine kinase, FLT3, BCL-2, IDH1, IDH2, are biomarker-driven chemotherapy-free agents approved for several major hematological malignancies." (PMID 33879198, 2021). "Our results suggested that the expression of BTK was decreased in the advancing stages of LUAD patients, which seemed to be inconsistent with hematological malignancies." (PMID 32351880, 2020). "Ibrutinib is a selective covalent Bruton’s tyrosine kinase (BTK) inhibitor, which could penetrate blood-brain barrier and approved by the Food and Drug Administration (FDA) in 2013 as a treatment of several hematological malignancies." (PMID 34605340, 2021).
hematologic cancers (13 papers, 2016 to 2026). "Despite significant advances in the treatment of hematologic cancers with BTK inhibitors (e.g., ibrutinib) and BCL-2 inhibitors (e.g., venetoclax), resistance and disease relapse remain major challenges." (PMID 41479906, 2025). "B-cell lymphoid malignancies are a heterogeneous group of hematologic cancers, where Bruton’s tyrosine kinase (BTK) inhibitors have received FDA approval for several subtypes." (PMID 39456530, 2024). "We further demonstrate that the lead compound has potentialto inhibit the proliferation of several hematological cancers andto induce the degradation of BTK." (PMID 36407952, 2022). "Ibrutinib is intended for selected hematologic cancers; it is a first-in-class, potent, orally administered drug, that covalently binds to Bruton’s tyrosine kinase (BTK) and inhibits B-cell antigen receptor signalling downstream of BTK." (PMID 29201288, 2017). "Related studies also indicate that treatment of hematologic cancer cells with proteasome inhibitors activates Bruton tyrosine kinase (BTK)." (PMID 27229530, 2016). "Currently, five BTK inhibitors—ibrutinib, zanubrutinib, orelabrutinib, tirabrutinib, and acalabrutinib—have demonstrated remarkable efficacy and have been approved for the treatment of different types of hematological cancers." (PMID 38765016, 2024). "Taken together, these findings imply that combined inhibition of BTK and IDH1 along with IMiDs can be regarded as effective treatment strategies to enhance the efficacy against hematological cancer cells and offer an alternative way to tackle acquired resistance." (PMID 41050081, 2025).
blood cancers (7 papers, 2018 to 2026). "Bruton’s tyrosine kinase (BTK), another TEC family member, has been successfully targeted in a variety of blood cancers with the covalent BTK inhibitor ibrutinib in the clinic." (PMID 38177131, 2024). "An example of a promising approach is the use of Bruton’s tyrosine kinase (BTK) inhibitors, such as ibrutinib, which was developed to treat several blood cancers, but has recently been shown to act effectively in solid tumours." (PMID 36012949, 2022). "To date, peripheral chronic inflammatory diseases and blood cancers have been the primary clinical applications of BTK inhibitors currently approved or in development." (PMID 30758770, 2019). "Moreover, though several dozen NF-κB inhibitors are under development, ~ 35% of them target Bruton tyrosine kinase, whose clinical indication is still blood cancer." (PMID 36720900, 2023).
bacterial infections (5 papers, 2019 to 2026). "Thus, male patients with a low B cell percentage and increased susceptibility to bacterial infections should be screened for the BTK mutation." (PMID 33013854, 2020). "BTK is a critical therapeutic target for a variety of viral and bacterial infections." (PMID 36362264, 2022).
brain disease (4 papers, 2018 to 2025). "Considering the various cell types that have been implicated in the pathogenesis of SLE, therapeutic BTK inhibition would largely directly affect B cells and macrophages, both of which have been implicated in skin and brain disease." (PMID 29370834, 2018). "In this paper, we provide an overview of the less explored roles of BTK in several brain diseases and discuss the potential of its inhibition to become a therapeutic target for neurological diseases." (PMID 40432438, 2025). "Therapeutic targeting of BTK by its inhibitors in inflammatory CNS disorders or treatment of autoimmune diseases is an emerging strategy that holds huge potential and can support current treatments of several neurological disorders and bring new paradigms toward brain disease." (PMID 40432438, 2025). "Several studies have examined the effect of BTK inhibition on SLN mice and found that BTK inhibition ameliorates renal, skin, and brain disease in MRL/lpr mice." (PMID 35874767, 2022). "We used a novel inhibitor of Bruton’s tyrosine kinase (BTK), BI-BTK-1, to target both macrophage and B cell function in the MRL-lpr/lpr murine model of SLE, and examined the effect of treatment on skin and brain disease." (PMID 29370834, 2018).
cardiovascular disease (4 papers, 2022 to 2025). "Patients with significant cardiovascular disorders or with concomitant warfarin or equivalent vitamin K antagonist treatment were excluded from clinical trials, and limited data are available for this population, despite their relevance given the known effects of first-generation BTK inhibitors." (PMID 40736551, 2025).
kidney disease (3 papers, 2013 to 2018). "We showed here that prophylactic BTK inhibition ameliorates NTN-mediated kidney disease." (PMID 27192942, 2016).
cardiac disease (2 papers, 2025 to 2026). "Cardiologic consultation should therefore probably be sought only in patients in whom treatment with Bruton tyrosine kinase inhibitors is considered the best possible option but who have signs and symptoms of possible cardiac disease." (PMID 40723186, 2025).
infectious disease (2 papers, 2020 to 2024). A disorder directly resulting from the presence and activity of a microbial, viral, or parasitic agent in humans. "The ongoing exploration of the immunological effects of BTKis will lead to the development of novel therapies that fully utilize the potential of BTK inhibition in the fields of oncology as well as autoimmune and infectious diseases." (PMID 39518015, 2024). "Furthermore, the gene expression profiles matched those of several infectious diseases including influenza virus infection, and upstream regulator analysis predicted both TLR7 and TLR9 as positive regulators and BTK as a negative regulator of gene expression." (PMID 33240770, 2020).
inflammation (2 papers, 2022 to 2023). Aberrant reaction of the microcirculation characterized by movement of fluid and leukocytes from the blood into extravascular tissues. "A deficiency of BTK in alveolar neutrophils was shown to protect mice from lung inflammation, and BTK was also found to be markedly elevated during NK cell maturation and activation." (PMID 36362264, 2022). "Other research demonstrates that ibrutinib reduces the activation of NF-κB and NLRP3 inflammasomes by targeting BTK and finally ameliorates pulmonary inflammation, suggesting that BTK might be a potential drug target for anti-inflammation." (PMID 37630287, 2023).
neurodegenerative disease (2 papers, 2019 to 2022). A disorder of the central nervous system characterized by gradual and progressive loss of neural tissue and neurologic function. "The role of BTK in neurodegenerative disease has not been well explored to date." (PMID 30758770, 2019). "However, the role of BTK in microglia, the resident innate immune cells of the central nervous system, and its involvement in the pathobiology of neurodegenerative disease has not been explored." (PMID 30758770, 2019).
neurological disease (2 papers, 2023 to 2025). "Nevertheless, the recent findings on BTK and the efficacy of BTKi in neurological diseases, especially in MS and AD, may be a promising start for these molecules to become potential candidates in neurological disease targeting." (PMID 40432438, 2025).
head and neck tumor (1 paper, 2023). "We describe the expression of the oncogenic BTK isoforms p80 and p65 in head and neck tumor tissue, whereby BTK-p65 is highly abundant in metastatic head and neck tumor cases." (PMID 37685940, 2023). "Most interestingly, over 80% of analyzed metastatic head and neck tumor cases revealed medium or high BTK-p65 staining, suggesting an oncogenic function of BTK-p65 in metastatic processes." (PMID 37685940, 2023).
intestinal disorder (1 paper, 2021). A non-neoplastic or neoplastic disorder that affects the small or large intestine. "Patients with mutations in Bruton’s tyrosine kinase (BTK) is known to manifest high prevalence of intestinal disorders including IBD." (PMID 33931590, 2021).
peripheral neuropathy (1 paper, 2021). A disorder affecting the peripheral nervous system. "The addition of the Bruton tyrosine kinase (BTK) inhibitor ibrutinib to R-CHOP therapy results in increased toxicity versus R-CHOP alone, including higher incidence of peripheral neuropathy." (PMID 34080039, 2021).